PRR11 (proline rich 11)
Description:
Plays a critical role in cell cycle progression.
Synonyms: FLJ11029
Tractability: PROTAC: UniProt records ubiquitination sites on it; ubiquitination databases record sites on it.
Gene: Protein-coding gene on chromosome 17 (59,155,732 to 59,206,709, forward strand). Ensembl gene ENSG00000068489.
Subcellular location: Cytoplasm; Nucleus
Subcellular location (Human Protein Atlas): Endoplasmic reticulum
Gene Ontology:
Biological process: regulation of cell cycle
Cellular component: cytoplasm; membrane; nucleus
Genetic constraint (gnomAD): Loss-of-function variants: 29 observed, 41.39 expected, observed/expected ratio (o/e) 0.7, 90% interval 0.52 to 0.95. The upper end of that interval is the gene's LOEUF score, 0.95, which puts it in group 4 of 6, group 1 being the genes least tolerant of losing a copy. Missense variants: 361 observed, 425.82 expected, observed/expected ratio (o/e) 0.85, 90% interval 0.78 to 0.93. Synonymous variants: 127 observed, 156.72 expected, observed/expected ratio (o/e) 0.81, 90% interval 0.7 to 0.94.
Homologues: Orthologues: chimpanzee PRR11 (99% identical), macaque PRR11 (95% identical), dog PRR11 (82% identical), rabbit PRR11 (77% identical), pig PRR11 (75% identical), mouse Prr11 (74% identical), rat Prr11 (73% identical), guinea pig PRR11 (71% identical), tropical clawed frog prr11 (33% identical), zebrafish prr11 (28% identical). Paralogues in human: JMY (21% identical), WHAMM (20% identical).
Diseases named in the same sentence as PRR11 in open-access papers:
PRR11 is named in the same sentence as 54 diseases in open-access papers, as found by Europe PMC text mining. Sharing a sentence is not in itself a finding about the gene and the disease. The quoted sentences say what the papers report.
breast carcinoma (20 papers, 2020 to 2025). "PRR11 has been shown to be associated to several types of cancer, including ovarian cancer, gastric cancer, breast cancer, hilar cholangiocarcinoma, pancreatic cancer and CC." (PMID 39583185, 2025). "Integrative analyses, including clinical data from patients with ER+ breast cancer treated with an aromatase inhibitor strongly implicated a role for PRR11 in endocrine resistance." (PMID 33127913, 2020). "Further, PRR11 amplifications were mutually exclusive of PIK3CA mutations in genomic breast cancer databases." (PMID 33127913, 2020). "We show herein that high PRR11 is causally associated with estrogen-independent growth of ER+ breast cancer cells." (PMID 33127913, 2020). "In this report, our comprehensive analysis with survival data of patients with ER+ breast cancer suggests that PRR11 is strongly associated with breast cancer progression." (PMID 33127913, 2020). "Recent studies have shown that PRR11 is implicated in the formation of gastric cancer, breast cancer, and hilar cholangiocarcinoma." (PMID 33276775, 2020). "Moreover, PRR11 is potentially associated with various cancers, such as lung, kidney, and breast cancer." (PMID 40062654, 2025). "Amplification of PRR11 was predominant in breast cancer, Pleural Mesothelioma, cholangiocarcinoma, and pheochromocytoma, while deep deletion was prevalent in prostate cancer." (PMID 40062654, 2025). "The nuclear transcription factor Y (NFY) is a cancer-promoting gene that enhances the value-added invasion and metastasis of breast cancer by promoting the expression of proline-rich 11 (PRR 11)." (PMID 39376611, 2024). "PRR11 was also demonstrated to promote anti-estrogen resistance in breast cancer by amplifying the PI3K signaling pathway." (PMID 34488538, 2021). "In this study, the authors demonstrate that PRR11 located at 17q23, is critical for conferring endocrine resistance through activation of PI3K signalling and therefore propose PI3K inhibition as a treatment for PRR11-amplified breast cancers." (PMID 33127913, 2020). "Next, overexpression of PRR11 in breast epithelial and breast cancer cells stimulated growth and this effect was abolished by RNA interference of p110α and by treatment with PI3K inhibitors." (PMID 33127913, 2020). "With the exception of SKP2 and CDKN1A, expression of each of these genes was significantly elevated in ER+ breast cancers with PRR11 copy number gain/amplification in the METABRIC and TCGA dataset." (PMID 33127913, 2020). "This suggests that genes overexpressed in PRR11 amplified ER+ breast cancers can be downregulated by perturbations that inhibit PI3K/AKT." (PMID 33127913, 2020). "The rate of PRR11 amplification is 15.9% in the Metastatic Breast Cancer (MBC) project, but 9.5% and 9.4% in METABRIC and The Cancer Genome Atlas (TCGA), respectively." (PMID 33127913, 2020). "We finally verified PRR11 amplification by fluorescence in situ hybridization (FISH) in a letrozole-resistant primary breast cancer." (PMID 33127913, 2020). "In recent years, PRR11 has been reported to serve as a candidate oncogene in various types of cancer, including pancreatic cancer, breast cancer, non-small cell lung cancer, hepatocellular carcinoma and ovarian carcinoma." (PMID 32565988, 2020). "In the METABRIC cohort, PRR11 copy number gain or amplification predicted shorter disease-free survival of patients with ER+/HER2− breast cancer treated with antiestrogens (HR = 1.408; 95% CI, 1.029–1.926)." (PMID 33127913, 2020). "Taken together, these data suggest a combination of PI3K and ERα targeted therapies is a rational approach against ER+ breast cancers with PRR11 amplification." (PMID 33127913, 2020). "PRR11 promotes estrogen-independent proliferation and confers endocrine resistance in ER+ breast cancers." (PMID 33127913, 2020). "In summary, we identified PRR11, a gene in the 17q23 amplicon, as a potential driver of antiestrogen resistance in ER+ breast cancer." (PMID 33127913, 2020).
breast carcinoma (continued). "Other studies have reported a significantly high expression of PRR11 in a number of types of cancer, such as lung cancer, ovarian cancer, carcinoma of the tongue, gastric cancer, breast cancer, hilar cholangiocarcinoma, colorectal cancer, pancreatic cancer and osteosarcoma." (PMID 39583185, 2025). "In addition, our recent work revealed that copy number amplification of Proline-rich 11 (PRR11) promotes resistance to endocrine therapy in ER+ breast cancers." (PMID 35784388, 2022). "Finally, among 67 genes in 17q23, high PRR11 mRNA levels also correlated with a shorter RFS in patients with ER+/HER2− breast cancer treated with endocrine therapy in the Kaplan–Meier Plotter database." (PMID 33127913, 2020). "It has reported that overexpression of PRR11 could promote breast cancer progression by activating EMT." (PMID 32565988, 2020). "Finally, in the METABRIC and TCGA datasets, PRR11 amplification and PIK3CA mutations were mutually exclusive of each other in ER+ breast cancers." (PMID 33127913, 2020). "Furthermore, breast cancer cell lines with PRR11 amplification displayed significantly higher sensitivity to the PI3K inhibitor pictilisib compared to cell lines without PRR11 amplification in the LINCS MGH/Sanger dataset of Drug/Cell-line Browser (DCB42)." (PMID 33127913, 2020). "We hypothesized that PRR11 amplification in the 17q23 amplicon promotes endocrine resistance in ER+ breast cancer." (PMID 33127913, 2020). "Currently, studies on PRR11 and SKA2 mainly focus on lung and breast cancer; however, the role of PRR11 and SKA2 in ESCC remains unclear." (PMID 32565988, 2020). "Moreover, we observed that PRR11-amplified breast cancer cell lines express higher levels of PRR11 protein compared to non-amplified cell lines (n = 11)." (PMID 33127913, 2020). "Similarly, in prostate cancer, osteosarcoma, pancreatic cancer and breast cancer, miR-195, miRNA-211-5p, miR-204-5p and miR-144-3p directly targeted PRR11 3′-UTR to participate in cellular activities, including proliferation, migration, cell cycle, apoptosis and angiogenesis." (PMID 36551227, 2022). "Furthermore, PRR11 was involved in the treatment of ultrasonic irradiation for breast cancer." (PMID 36551227, 2022). "Finally, we propose that, in conjunction with endocrine therapy, PI3K may be an actionable target in ER+ breast cancers harboring PRR11 amplification." (PMID 33127913, 2020). "PRR11 and SKA2 gene pair are overexpressed in breast cancer and esophageal carcinoma, which accelerate proliferation, migration, and invasive capabilities." (PMID 34993016, 2021). "The role of the PRR11 and SKA2 gene pair has been described in various types of cancer, including breast cancer, non-small cell lung cancer, hepatocellular carcinoma and ovarian carcinoma." (PMID 32565988, 2020). "PRR11-amplified breast cancer cells rely on PIK3CA and are highly sensitive to PI3K inhibitors, suggesting that PRR11 amplification confers PI3K dependence." (PMID 33127913, 2020). "The data shown so far suggest that a potential oncogenic role of PRR11 depends on activation of PI3K and, as such, PI3K inhibitors would be effective against PRR11-overexpressing breast cancer cells." (PMID 33127913, 2020). "Knockdown of PRR11 and SKA2 inhibited migration and invasion of breast cancer cells." (PMID 37752518, 2023). "In addition to finding PRR11-related mechanisms, the original study reported a cluster of E2F4-regulated genes that were sensitive to subsequent CDK4/6 inhibitor (palbociclib) treatment in a separate cohort of ER+ breast cancer patients." (PMID 39057065, 2024). "Finally, PRR11-amplified breast cancer cell lines exhibited higher sensitivity to PI3K inhibitors compared to cells that do not harbor PRR11 amplification." (PMID 33127913, 2020).
breast carcinoma (continued). "PRR11 ablation did not suppress proliferation in PRR11-overexpressing triple negative and HER2+ breast cancer cells." (PMID 33127913, 2020).
lung carcinoma (16 papers, 2015 to 2025). "PRR11 is a candidate oncogene that has been implicated in the pathogenesis of lung cancer, gastric cancer and hilar cholangiocarcinoma." (PMID 30115812, 2018). "Consistently, knockdown of PRR11 in lung cancer cells causes inhibition of proliferation, motility and colony formation ability accompanied with the dysregulation of multiple critical pathways and genes involved in the cell cycle, tumorigenesis and metastasis." (PMID 28257042, 2017). "PRR11 is a potential candidate oncogene that has been implicated in the pathogenesis of lung cancer, however the role of PRR11 in gastric cancer is currently unclear." (PMID 26252227, 2015). "Higher expression of PRR11 is significantly associated with poor prognosis in lung cancer patients." (PMID 28257042, 2017). "Additionally, in silico analysis has suggested that high expression of PRR11 is significantly associated with poor prognosis in lung cancer patients." (PMID 25971332, 2015). "Furthermore, our results also supported that inhibited PRR11 could cause cell arrest in S phase, which is similar to that in lung cancer cells and tongue squamous carcinoma." (PMID 36060253, 2022). "Based on the literature, PRR11 overexpression affects the cell cycle and promotes lung cancer progression, and the onset and development of CC." (PMID 39583185, 2025). "Recent mechanistic studies showed that PRR11 promoted lung cancer development by regulating the expression of cell cycle–related genes." (PMID 34499617, 2021). "RNAi-mediated silencing of PRR11 caused S phase arrest and suppressed cellular proliferation and colony formation ability in lung cancer cells, demonstrating that PRR11 had a critical role in both cell cycle progression and tumorigenesis." (PMID 34497684, 2021). "The PRR11 protein was first identified by Ji and colleagues in lung cancer as a protein that functions periodically and specifically promotes S-phase progression of the cell cycle." (PMID 33276775, 2020). "Our previous study was the first to isolate and identify proline-rich protein 11 (PRR11) as a novel cancer-related gene that is implicated in both cell cycle progression and lung cancer development." (PMID 28257042, 2017). "On the other hand, PRR11 expression is aberrantly upregulated at both mRNA and protein levels in primary lung cancer tissues compared with normal lung tissues." (PMID 28257042, 2017). "Proline-rich Protein 11 (PRR11), a candidate oncogene, has been implicated in cell cycle progression and tumorigenesis of lung cancer." (PMID 25971332, 2015). "In lung cancer, silencing PRR11 induced S-phase arrest, inhibition of cell proliferation and invasion and especially tumor growth." (PMID 25971332, 2015). "While PRR11 was reportedly up-regulated in lung cancer, the possible mechanisms for this increased expression has not been reported, and, moreover, much work is necessary to evaluate the clinical significance of PRR11." (PMID 26252227, 2015). "Through regulating important genes involved in cell cycles and tumorigenesis, PRR11 participates in the initiation and progression of lung cancer and epithelial-to-mesenchymal transition in breast cancer." (PMID 26252227, 2015). "The expression profile of PRR11 has been investigated in lung cancer, and the protein appears tobe involved in progression of the cell cycle." (PMID 25971332, 2015). "Furthermore, there is evidence to indicate that PRR11 is a potential target for anticancer therapies in hilar cholangiocarcinoma and lung cancer." (PMID 39583185, 2025).
lung carcinoma (continued). "Also, smoking-related genes like PRR11 and PRR11 co-expressed genes were analysed as potential predictors of lung cancer and for the potential efficacy of immune checkpoint therapy." (PMID 39123419, 2024). "PRR11 is also up-regulated in other types of cancer, such as breast, head and neck, and lung cancer, and its expression in sarcoma is particularly striking, which may be a new discovery." (PMID 36739300, 2023). "Other studies have indicated that PRR11 knockdown could inhibit tumor occurrence by inducing autophagy in lung cancer cells." (PMID 34499617, 2021). "Also, PRR11 silencing leads to cell cycle arrest, suppresses colony formation, decreases cell proliferation and inhibits tumorigenic potential of lung cancer cells." (PMID 32565988, 2020). "Moreover, PRR11 knockdown also reduces tumor growth in vivo in the xenograft nude mouse model of lung cancer." (PMID 28257042, 2017). "PRR11 was found to be over-expressed in about half lung cancer specimens." (PMID 25971332, 2015). "The previous study of PRR11 was conducted and interpreted in the setting of lung cancer and showed that PRR11-knockdown dysregulated the expression of multiple important gene in critical pathways such as cell cycle, tumorigenesis and metastasis (e.g. CCNA1, RRM1, MAP4K4 and EPB41L3)." (PMID 26252227, 2015). "PRR11 is a relatively novel protein molecular that may play a role in cancer pathogenesis, and there is currently only few articles describing the role of PRR11 in lung cancer." (PMID 26252227, 2015). "Consequently, PRR11 represents a potential therapeutic target for lung cancer treatment." (PMID 38281298, 2024). "PRR11 is a newly identified oncogene in lung cancer, yet its role in others tumors remains unclear." (PMID 25971332, 2015). "Consistently, the elevated expressions of PRR11 and SKA2 in lung cancer are highly correlated with each other as well as with that of NF-Y." (PMID 28257042, 2017). "In addition, the PRR11 and SKA2 gene pair has been hypothesized as a potential new target for the diagnosis and treatment of lung cancer." (PMID 32565988, 2020).
hepatocellular carcinoma (15 papers, 2015 to 2025). A malignant tumor that arises from hepatocytes. "The lncRNA, AC099850.3, promotes hepatocellular carcinoma proliferation and invasion through the PRR11/PI3K/AKT axis and is associated with patient prognosis, indicating that it is an important prognostic indicator." (PMID 35692827, 2022). "The LncRNA AC099850.3 promotes hepatocellular carcinoma proliferation and invasion through the PRR11/PI3K/AKT axis and is associated with patients’ prognosis." (PMID 36104680, 2022). "And AC099850.3 significantly promoted migration, invasion and proliferation of hepatocellular carcinoma cell through the PRR11/PI3K/AKT pathway." (PMID 36211292, 2022). "AC099850.3 has been found to promote proliferation and invasion in hepatocellular carcinoma via the PRR11/PI3K/AKT pathway and is also a major participant in prognostic models for squamous cell carcinoma of the tongue and non-small-cell lung cancer." (PMID 36065303, 2022). "However, the biological mechanism of lncRNA AC099850.3 as an oncogene in hepatocellular carcinoma via PRR11/PI3K/AKT axis is still uncertain." (PMID 36551227, 2022). "PRR11-positive expression was observed in 93.0% esophageal primary tumors, 64.6% gastric tumors, 64.5% colorectal tumors, 87.7% pancreatic ductal carcinomas, 53.3% hepatocellular carcinomas and 63.3% hilar cholangiocarcinoma." (PMID 25971332, 2015). "Cuproptosis-related lncRNA AC099850.3 is a prognostic marker for hepatocellular carcinoma (HCC) and has been confirmed to promote HCC progression via the PRR11/PI3K/AKT axis." (PMID 37529698, 2023). "AC099850.3 has been confirmed to promote hepatocellular carcinoma (HCC) proliferation and invasion via the PRR11/PI3K/AKT axis and is a prognostic marker for HCC." (PMID 36212459, 2022). "One recent study revealed that overexpression of lncRNA AC099850.3 could promote cell proliferation and invasion via the PRR11/PI3K/AKT pathway, predicting a poor prognosis in hepatocellular carcinoma." (PMID 36457749, 2022). "Significant differences in PRR11 expression between normal tissues and tumors were observed in esophageal squamous cell cancer (ESCC), gastric cancer (GC), colorectal cancer (CRC), pancreatic ductal cancer (PDC), and hilar cholangiocarcinoma (HC), but not in hepatocellular carcinoma (HCC)." (PMID 25971332, 2015).